JAK1 (Janus kinase 1)
Diseases named in the same sentence as JAK1 in open-access papers (continued):
Sharing a sentence is not in itself a finding about the gene and the disease.
polycystic ovary syndrome (2 papers, 2023). A disorder that manifests as multiple cysts on the ovaries. "LEP is a regulatory molecule involved in the polycystic ovary syndrome (PCOS) cell model and acts as an upstream regulator of JAK1/STAT3-related inflammation and apoptosis in insulin-treated ovarian granulosa cells (OGCs)." (PMID 38005265, 2023).
progeria (2 papers, 2020 to 2021). "Moreover, the JAK/STAT pathway regulates cellular senescence and some aging-associated alterations; indeed, the JAK1/2 inhibitor ruxolitinib alleviates age-related bone loss and adipose tissue inflammation in mice and rescues some premature aging phenotypes in progeria mouse models." (PMID 34824394, 2021). "In this study, we have described that inhibition of JAK1/2 by ruxolitinib improves some progeria phenotypes in normal human fibroblasts and in a murine model of progeria." (PMID 32196928, 2020).
renal fibrosis (2 papers, 2022 to 2023). A final common manifestation of a wide variety of chronic kidney diseases characterized by glomerulosclerosis and tubulointerstitial fibrosis. "Thus, the SOCS1/p-JAK1/p-STAT1 pathway contributes to renal fibrosis in folic acid-induced RIF mice." (PMID 35990680, 2022).
SAPHO syndrome (2 papers, 2025 to 2026). SAPHO syndrome (acronym for Synovitis, Acne, Pustulosis, Hyperostosis and Osteitis) is an auto-inflammatory disease, mainly characterized by the association of neutrophilic cutaneous involvement and chronic osteomyelitis. "This case illustrates the effectiveness of upadacitinib, a selective JAK1 inhibitor, for the rapid resolution of cutaneous and articular symptoms of SAPHO syndrome following unsuccessful IL-17A inhibition, offering valuable insights for management of refractory SAPHO syndrome." (PMID 41341579, 2025).
scleroderma (2 papers, 2021 to 2022). Scleroderma is a rare autoimmune connective tissue disorder characterized by abnormal hardening of the skin and, sometimes, other organs. "Two of the most used JAK inhibitors, tofacitinib (inhibits Jak1/3) and baricitinib (inhibits Jak1/2), were found to be effective in both human patients and scleroderma mouse models, although the direct mechanism is less clear." (PMID 34164359, 2021). "Our study indicates that the JAK1 and JAK2 inhibitor has stronger antifibrotic effects than the JAK3 inhibitor, and JAK2 inhibitor use also results in the loss of capillaries in BLM-induced scleroderma mice." (PMID 35733864, 2022). "JAK1 and JAK2 but not JAK3 inhibitors alleviated skin fibrosis in different aspects, such as morphology and dermal thickness, and the JAK2 inhibitor alleviated skin fibrosis the most, demonstrating that JAK inhibition prevented fibrosis in a BLM-induced mouse model of scleroderma." (PMID 35733864, 2022).
skin cancer (2 papers, 2018 to 2025). "NGS identified a new JAK3 p.M511I mutation in the recurrent skin tumor and new JAK1 p.L783F and subclonal JAK1 p.T901A mutations in the blood." (PMID 40231467, 2025). "Myricitrin has also been found to protect against skin cancer by strongly inhibiting tumour promoting-induced neoplastic cell transformation via restriction of MEK, JAK1, Akt, and MKK4 kinase activity." (PMID 29523111, 2018).
squamous carcinoma (2 papers, 2021 to 2024). "Consistently, JAK1 protein level also exhibited a dramatic increase in squamous carcinoma tissues compared to normal controls." (PMID 39099000, 2024). "In contrast to squamous carcinoma, neither STAT3 nor JAK1 presented any observable differences in adenocarcinoma tissues." (PMID 39099000, 2024).
stomach cancer (2 papers, 2017 to 2023). "Both endometrial and stomach tumors with JAK1 frameshifts also exhibited reductions in gene sets associated with immune surveillance such as the inflammatory response and antigen presentation." (PMID 29121062, 2017).
T-cell leukemia (2 papers, 2021 to 2024). A malignant disease of the T-lymphocytes in the bone marrow, thymus, and/or blood. "JAK1 Y605 is reported to be phosphorylated within the T cell leukemia Jurkat cell line treated with phosphatase inhibitor by the PhosphoSitePlus consortium." (PMID 38446738, 2024).
thromboembolic disease (2 papers, 2020 to 2025). "Ruxolitinib is a JAK1/JAK2 inhibitor that has been proposed as an alternative treatment in HU‐intolerant or resistant PV patients with lower thromboembolism risk." (PMID 40781888, 2025).
uterine cancer (2 papers, 2017 to 2025). Primary or metastatic malignant neoplasm involving the uterine corpus and/or the cervix. "We previously found somatic loss-of-function (LOF) JAK1 mutations in 9.5% of uterine cancer in Total Cancer Care (TCC@) tumors." (PMID 28977839, 2017). "Unorthodoxically, this study in NSCLC and the previous studies of JAK1 in uterine cancer also suggest that JAK1 and JAK2 have tumor suppressor function, deficiencies of them could allow tumor cells to escape T-cell mediated immune surveillance." (PMID 28977839, 2017).
vaginal infection (2 papers, 2021 to 2022). "The mechanisms of the effects of vaginal infections induced by E. coli on pregnancy outcome revealed that macrophages located at the maternal-foetal interface might have a crucial effect and further affect pregnancy outcomes through the IL-4/JAK-1/STAT-6 signalling pathway." (PMID 35090514, 2022).
ZIKV infection (2 papers, 2017 to 2022). "We found that ZIKV infection induced weak activation of Jak1 and STAT1, and reduced the phosphorylation of Jak1 and STAT1 after IFNβ stimulation." (PMID 28373913, 2017). "Interestingly, we found that ZIKV infection only reduced the protein level of Jak1 but not STAT1, while it had little effect on the mRNA level of Jak1." (PMID 28373913, 2017).
alveolitis (1 paper, 2020). "Compared with the BLM group, the degree of alveolitis and fibrosis improved significantly, and the expression of p-JAK1 and p-STAT1 decreased; conversely, the expression of SOCS3 increased in the treatment group." (PMID 32908556, 2020).
Alzheimer disease (1 paper, 2025). A progressive, neurodegenerative disease characterized by loss of function and death of nerve cells in several areas of the brain leading to loss of cognitive function such as memory and language. "In addition, studies have uncovered the molecular interactions between compounds derived from Sanghuangporus and Alzheimer’s disease; within Sanghuangporus, 374 disease-related targets have been identified, including crucial ones such as JAK1, LCK, MAPK1, STAT3, and STAT1." (PMID 39997416, 2025).
aortitis (1 paper, 2024). Inflammation of the aorta. "Tofacitinib, a JAK inhibitor (JAKi) that predominantly inhibits JAK1 and JAK3 molecules has been shown to ameliorate aortitis due to GCA by inhibiting the action of T lymphocytes." (PMID 38334659, 2024).
autism spectrum disorder (1 paper, 2023). A spectrum of developmental disorders that includes autism, and Asperger syndrome. "The findings of this study pointed to the existence of a correlation between the levels of expression of the genes JAK1 and IL-6 and the severity of autism spectrum disorder (ASD)." (PMID 38026692, 2023).
autoimmune uveitis (1 paper, 2025). An autoimmune form of uveitis (disease). "An animal model study demonstrated upregulation of JAK1-mediated signaling cascades in autoimmune uveitis, supporting the therapeutic potential of selective JAK1 inhibitors in this context." (PMID 41366179, 2025).
Autosomal dominant hyper-IgE syndrome (1 paper, 2021). 2000 IU/ml), recurring staphylococcal skin abscesses, and recurrent pneumonia with formation of pneumatoceles. "Using the JAK1/2 inhibitor ruxolitinib, along with cells from patients with STAT3 loss of function (STA3 LOF; autosomal dominant hyper IgE syndrome) we examined the role of JAK/STAT signaling in the hyperproliferation and metabolic dysregulation seen in keloid fibroblasts." (PMID 33662027, 2021).
bile reflux (1 paper, 2022). "Bile reflux can promote gastric carcinogenesis through the activation of the IL‐6/JAK1/STAT3 pathway and STAT3 inhibition can alleviate this carcinogenic effect." (PMID 35285172, 2022).
bladder tumors (1 paper, 2017). "Downstream IL-6 signaling JAK1, STAT3, and SOCS3 were consistently upregulated in the same bladder tumors with low IL-6 levels suggesting IL-6 independent activation of the JAK1/STAT3 pathway." (PMID 29242529, 2017).
Blau syndrome (1 paper, 2026). Blau syndrome (BS) is a rare systemic inflammatory disease characterized by early onset granulomatous arthritis, uveitis and skin rash. "Granulomatous inflammation in Blau syndrome is mediated by IFN-γ and sustained JAK-STAT activation, making JAK1/2 inhibition a rational therapeutic target." (PMID 41601685, 2026).
blood disease (1 paper, 2022). A disease that occurs in the blood. "To further understand the mechanisms underlying p.A634D JAK1GOF–mediated allergic inflammation, we evaluated the effects of enhanced JAK1 signaling on hematopoiesis using zebrafish (Danio rerio) — a powerful model of human blood disease." (PMID 36546480, 2022).
bone marrow cancer (1 paper, 2014). "As mentioned in Section 3.2, Ruxolitinib, an FDA-approved drug for treatment of a type of bone marrow cancer, is a JAK1/2 inhibitor." (PMID 24550933, 2014).
cardiac hypertrophy (1 paper, 2025). "Loss of cardiomyocyte JAK1 resulted in dilated cardiomyopathy in aged mice characterized by cardiac hypertrophy, impairment of left ventricular systolic function, and myocardial fibrosis." (PMID 40744288, 2025). "Future studies with inducible cell-type specific deletion of Jak1 in adult mice will help uncover the translational potential of targeting JAK1 in cardiac hypertrophy and failure." (PMID 40744288, 2025). "In the context of cardiac hypertrophy, inhibition of STAT3 signaling is generally protective, suggesting antagonizing JAK1 signaling in adulthood may even be antihypertrophic and cardioprotective." (PMID 40744288, 2025). "JAK1 is particularly important for STAT3-dependent cytokine production and macrophage recruitment by cardiomyocytes and STAT3 promotes cardiac hypertrophy and remodeling in response to pressure overload or angiotensin-II but is protective during ischemic injury." (PMID 40744288, 2025).
cataract (1 paper, 2025). Partial or complete opacity of the crystalline lens of one or both eyes that decreases visual acuity and eventually results in blindness. "Mechanically, NR2F1 proteins directly interacted with the promoter region of STAT3 and orchestrated the up-regulation of phosphorylated STAT3 (p-STAT3), thereby facilitating the apoptosis and migration of SRA01/04 cells via the JAK1/STAT3 pathway, resulting in epithelium fibrosis and cataracts." (PMID 40641526, 2025).
chronic eosinophilic leukemia (1 paper, 2025). "A new case of chronic eosinophilic leukemia is sensitive to JAK1 inhibitor treatment and has a JAK1 R629D630del mutation, located in the flexibility changed PK region." (PMID 40868963, 2025).
chronic neutrophilic leukemia (1 paper, 2022). A rare chronic myeloproliferative neoplasm characterized by neutrophilic leukocytosis. "Besides, it has also been proposed for use in patients with chronic neutrophilic leukemia for its safety and efficacy in inhibiting JAK1/2." (PMID 35241019, 2022).
chronic thromboembolic pulmonary hypertension (1 paper, 2024). Chronic thromboembolic pulmonary hypertension (CTEPH) is characterized by the persistence of thromboemboli in the form of organized tissue obstructing the pulmonary arteries. "The involvement of the JAK/STAT cascade in inflammation and fibrosis in lung tissue has driven studies on the use of the JAK1 and JAK2 inhibitor ruxolitinib in chronic thromboembolic pulmonary hypertension." (PMID 39684570, 2024).
condyloma acuminatum (1 paper, 2025). "This case underscores the potential for JAK1 inhibition to impair cellular antiviral immunity, particularly in the context of human papillomavirus (HPV)-related diseases such as condyloma acuminatum." (PMID 41466898, 2025). "Upadacitinib, a selective JAK1 inhibitor, may impair cellular immunity necessary for HPV clearance, potentially leading to treatment-resistant or persistent condyloma acuminatum." (PMID 41466898, 2025).
contact dermatitis (1 paper, 2019). An inflammatory skin condition caused by direct contact between the skin and either an irritating substance or an allergen. "Accordingly, mouse models for contact dermatitis show positive response to treatment with topical tofacitinib (JAK1/JAK3i), thus suggesting a possible application of topical JAKi also in humans." (PMID 31849996, 2019).
COPA syndrome (1 paper, 2022). "Recently published case reports show treatment of COPA syndrome patients with JAK1/2 inhibitors ruxolitinib, baricitinib and upadacitinib." (PMID 35484149, 2022).
cystitis (1 paper, 2023). Inflammation of the urinary bladder. "Despite higher basal values of Jak1 vs. Jak3 mRNA in the bladders of Ctrl animals, it appears that the JAK/STAT pathway is not activated via JAK1 in CYP-induced cystitis." (PMID 36982831, 2023).
dilated cardiomyopathy (1 paper, 2025). Cardiomyopathy which is characterized by dilation and contractile dysfunction of the left and right ventricles. "Loss of JAK1 in cardiomyocytes results in dilated cardiomyopathy by 6 months of age, indicating cytokine receptor signaling through JAK1 is essential for cardiac physiology." (PMID 40744288, 2025). "Here we found that perinatal loss of JAK1 in cardiomyocytes is detrimental, with dilated cardiomyopathy developing in cardiomyocyte Jak1-deleted mice by 6 months of age." (PMID 40744288, 2025). "Conditional deletion of Jak2 in cardiomyocytes results in dilated cardiomyopathy, similar to the phenotype reported here for conditional loss of Jak1, indicating indispensable and nonredundant functions for both JAK1 and JAK2 in cardiac myocytes." (PMID 40744288, 2025).
dry eye (1 paper, 2025). "While these results are based on a rat corneal injury model and require confirmation in human studies, they suggest that JAK1, SKI, and ZBTB16 could represent candidate biomarkers for future diagnostic assays or targets for immunomodulatory therapy in dry eye." (PMID 40940727, 2025). "Upregulation of key mediators, such as JAK1, SKI, and ZBTB16, paralleled increased IL-6, IL-1β, and TNF-α expression, implicating innate immune activation in dry eye pathogenesis." (PMID 40940727, 2025).
endometrial adenocarcinoma (1 paper, 2017). "In endometrial adenocarcinoma (UCEC), 3/321 (0.9%) MSS samples, 4/44 (9.1%) MSI-L samples, and 79/169 (46.7%) MSI-H samples had a frameshift alteration in JAK1, which was statistically significant when comparing MSS and MSI-H (P < 0.0001, Fisher’s exact test)." (PMID 29121062, 2017).
Endometrial tumors (1 paper, 2017). "To further assess if the JAK1 frameshift mutations were loss of function events, we evaluated expression of JAK1 mRNA in endometrial tumors from TCGA and endometrial cell lines from the CCLE." (PMID 29121062, 2017). "Using The Cancer Genome Atlas (TCGA) data of MSI-H endometrial tumors, we found reduced expression of gene sets associated with interferon gamma, interferon alpha, IL-6, and IL-2 responses in JAK1 frameshift mutants compared to JAK1 wild-type tumors." (PMID 29121062, 2017). "Eight hallmark gene sets were significantly downregulated in JAK1 frameshift samples and five of those were reduced in endometrial tumor samples including IFNα, IFNγ, inflammatory response, allograft rejection, and coagulation." (PMID 29121062, 2017). "JAK1 mRNA expression was significantly downregulated in both endometrial tumor samples and endometrial cell lines with a JAK1 frameshift compared to JAK1 wildtype endometrial samples (tumor: P < 10−18, cell line: P < 10−4, Mann-Whitney U test)." (PMID 29121062, 2017).
endometritis (1 paper, 2021). An acute or chronic, usually bacterial infectious process affecting the endometrium. "This is the first study of the role of the JAK1 signaling pathway in the treatment of endometritis by bAD-MSCs, and the results of this study offer a new therapeutic target for the treatment of bovine endometritis." (PMID 34746277, 2021).
endotoxemia (1 paper, 2023). "MRP8/14 induces sustained IP-10 production by activating the IFNβ-JAK1/TYK2-STAT1-IRF7 pathway, which subsequently attracts numerous CXCR3+ T cells and results in an exaggerated inflammatory response and lung injury in the context of endotoxemia." (PMID 37701855, 2023). "Based on this finding, we examined the function and mechanism of MRP8/14-induced late-phase IP-10 production in the context of endotoxemia and showed that MRP8/14 promoted inflammation and lung injury in the context of endotoxemia through the IFNβ-JAK1/TYK2-STAT1-IRF7-IP-10-CXCR3 signaling pathway." (PMID 37701855, 2023). "In vivo air pouch experiments confirmed that the IFNβ-JAK1/TYK2-STAT1-IRF7 pathway was required for chemokine (C-X-C motif) receptor 3 (CXCR3)+ T lymphocyte migration, which promoted lung injury in the context of endotoxemia." (PMID 37701855, 2023). "In summary, our study demonstrates that MRP8/14 induces sustained production of IP-10 via the IFNβ-JAK1/TYK2-STAT1-IRF7 pathway to attract CXCR3+ T lymphocytes into lung tissues and ultimately results in lung injury by an excessive inflammatory response in the context of endotoxemia." (PMID 37701855, 2023).
enteropathy (1 paper, 2023). "In combination with - in cancer therapy successfully tested - JAK inhibitors ruxolitinib (JAK1/2 inhibitor) and tofacitinib (JAK1/3 inhibitor), additional treatment success with resolution of enteropathy and respiratory function was achieved in five of eight patients." (PMID 37140667, 2023).
familial chilblain lupus (1 paper, 2020). An instance of Chilblain lupus that is caused by an inherited modification of the individual's genome. "JAK inhibition with tofacitinib (JAK3>JAK1>JAK2), baricitinib (JAK1/2) or ruxolitinib (JAK1/2) showed efficacy for familial chilblain lupus in human case studies and small clinical trials." (PMID 32714331, 2020).
Flavivirus Infections (1 paper, 2010). Infections with viruses of the genus FLAVIVIRUS, family FLAVIVIRIDAE. "WNV nonstructural proteins inhibit IFN-α/β signaling by preventing JAK1 and Tyk2 phosphorylation and IFN-β gene transcription, therefore the antiviral effects mediated by IFN during flavivirus infection primarily benefit uninfected cells in the vicinity of infected cells." (PMID 20661470, 2010).
Focal cortical dysplasia (1 paper, 2024). A type of malformation of cortical development that primarily affects areas of neocortex. "IL‐2 signaling pathway was activated in patients with focal cortical dysplasia (FCD), a cause of intractable epilepsy, and JAK1/3‐STAT5 was the downstream of IL‐2‐dependent signaling pathways contributing to the pathogenesis of FCD." (PMID 38357846, 2024).
folic acid deficiency (1 paper, 2023). "In conclusion, this study found that in the context of ischemia‐reperfusion, folic acid deficiency may trigger astrocytes' inflammatory response via the IL‐6/JAK‐1/pSTAT3 pathway." (PMID 36794521, 2023).
giant cell arteritis (1 paper, 2023). "JAK1 and JAK3 were involved in the chronic inflammation of media and large arteries in an animal model of giant cell arteritis (GCA)." (PMID 37384596, 2023).
gout (1 paper, 2026). A condition characterized by painful swelling of the joints, which is caused by deposition of urate crystals. "Experimental validation confirmed these findings: qPCR analysis demonstrated that the mRNA levels of JAK1, CSF1R, and NAMPT were significantly elevated in cellular models simulating both gout and MetS conditions." (PMID 42063773, 2026).